CLN3 (CLN3 lysosomal/endosomal transmembrane protein, battenin)
Diseases named in the same sentence as CLN3 in open-access papers (continued):
Sharing a sentence is not in itself a finding about the gene and the disease.
Anxiety (6 papers, 2017 to 2025). Intense feelings of nervousness, tension, or panic often arise in response to interpersonal stresses. "Participants with CLN3 disease had anxiety (11/17, 65%), attentional difficulties (6/17, 35%), aggression (6/17, 35%), repetitive behaviour (5/17, 29%), obsessions (4/17, 24%), hyperactivity (3/17, 18%) and impulsivity (3/17, 18%)." (PMID 39821609, 2025). "Based on present knowledge of triggering factors, the neural anxiety/fear circuit, its afferent and efferent pathways and documented CLN3 disease-impact on these tracks, the current study discusses a rational approach how to prevent and/or treat the attacks." (PMID 37771451, 2023). "Using a Cln3 knockout (Cln3Delta-ex1-6) mice model, an increased anxiety-related behavior has been demonstrated in older mice." (PMID 37771451, 2023). "From the connections between CLN3 disease symptoms and emotions, and from the fact that anxiety was noted in all UBDRS-files, it can be concluded that emotions play a key role in the behaviour of these children." (PMID 35627432, 2022). "We used Cln3 knockout (Cln3Δex1-6) mice and found increased anxiety-related behavior and impaired aversive learning as well as markedly affected motor function including disordered coordination." (PMID 29135436, 2017). "Based on present knowledge of triggering factors, the neural anxiety/fear circuit, its afferent and efferent pathways and the documented CLN3 disease-impact on these tracks, the current study presents and discusses a rational approach and strategy how to treat and/or prevent the attacks." (PMID 37771451, 2023).
dementia (6 papers, 2014 to 2025). Loss of intellectual abilities interfering with an individual's social and occupational functions. "While HOOK1 interacts with CLN3, the causative gene for the autosomal recessive Batten disease characterized by visual impairment, gait anomalies, seizures, dementia and sometimes mental deterioration, DNAJC6 has been shown to be implicated in Parkinson disease." (PMID 26997977, 2016). "Similarly, bilateral rapidly progressive vision loss, with or without childhood dementia and/or behavioural problems, in a very young child should immediately trigger testing, including CLN3 disease, to determine the cause." (PMID 40355884, 2025).
Stargardt disease (6 papers, 2018 to 2025). "We analyzed protracted and classical CLN3 separately and added a control group of patients diagnosed with juvenile onset macular degeneration (early onset Stargardt disease) to control for possible effects of rapid vision loss on neurocognitive functioning." (PMID 29392585, 2018). "The visual decline in children with CLN3 disease is frequently more rapid than other early onset maculopathies such as Stargardt disease." (PMID 36964447, 2023). "The unaffected (childhood) neurocognitive functioning in both protracted CLN3 disease and Stargardt disease patients with similarly early and severe visual deterioration delineates that low IQ test scores and poor school performance cannot be explained by severe vision loss alone." (PMID 29392585, 2018).
Atrophy (5 papers, 2017 to 2023). Any weakening or degeneration, especially through lack of use. "Magnetic resonance imaging (MRI) studies in JNCL mice reported that CLN3 protein deficiency results in a similar generalized atrophy of the brain, thereby mirroring the human condition." (PMID 28165011, 2017). "A hallmark of CLN3 disease is bull’s eye maculopathy (BEM), which describes a central area of atrophy, surrounded by concentric circles of diseased retina and then healthier retina peripherally." (PMID 33547385, 2021). "Other fundus findings reported in CLN3 disease include optic disc pallor, macular atrophy, macular striae, macular oedema, retinal pigment epithelium (RPE) atrophy, RPE granularity, bone spicule formation, epiretinal membrane, arteriolar attenuation, and even a Coats-like reaction." (PMID 36964447, 2023). "Importantly, the reduced RPE autofluorescence in the CLN3 disease donor eye was not a consequence of RPE atrophy/cell death, as decreased RPE autofluorescence was also observed in areas with intact RPE monolayer." (PMID 33547385, 2021).
breast carcinoma (5 papers, 2015 to 2022). "The association of CLN3 expression with specific clinicopathological characteristics of breast cancer patients is documented." (PMID 26528430, 2015). "Elevated expression of the CLN3 gene in breast cancer was significantly associated with HER2-negativity, when comparing cancerous to non-tumor tissue from reduction mammoplasties." (PMID 26528430, 2015). "Here, we determine CLN3 expression in non-tumor vs. tumor samples from fresh and formalin-fixed/paraffin-embedded (FFPE) breast tissue and analyze the association between CLN3 overexpression and different clinicopathological characteristics of breast cancer patients." (PMID 26528430, 2015). "The expression of CLN3 mRNA and CLN3 protein is increased in a variety of cancers, including breast cancer." (PMID 35186475, 2022). "The results showed that some of the genes related to the prognosis of breast cancer (IKBKB, ATG16L2, CLN3, MBTPS2, TSC2, and CAPN10) had a higher frequency of mutations." (PMID 34457116, 2021). "Predictably, CLN3 mRNA expression and CLN3 protein were up-regulated in a number of human and murine breast cancer-cell lines." (PMID 26528430, 2015). "In this study, CLN3 mRNA expression levels in breast cancer patient FFPE and fresh tissue samples were determined and association with patient characteristics established." (PMID 26528430, 2015). "So, 56% of breast cancer patients that exhibit overexpression of CLN3 mRNA lack HER2 expression compared to only 37% overexpressing HER2." (PMID 26528430, 2015). "The expression of CLN3 mRNA and CLN3 protein is increased in a variety of cancers, including prostate, ovarian, colon, glioblastoma, and, human breast cancer-cell lines and solid colon cancer." (PMID 26528430, 2015). "In addition, gene expression of enzymes controlling sphingolipid metabolism in fresh-frozen breast cancer tissues is established, confirming the CLN3-ceramide link." (PMID 26528430, 2015). "Moreover, several enzymes from the de novo ceramide synthesis pathway are differentially expressed in breast cancer, implicating ceramide and its upstream regulator, the CLN3 gene, in breast cancer." (PMID 26528430, 2015). "In conclusion, the expression of CLN3 is increased in human breast cancer." (PMID 26528430, 2015). "By using siRNAs targeting all three TETs, expression of CTSD and CLN3 was shown to be specifically repressed by TET2 in MCF-7 and T47D breast cancer cells and, to a lower extent, in HEK293T kidney cancer cells." (PMID 35351824, 2022). "Relationship between CLN3 mRNA overexpression and patient clinicopathological parameters of the FFPE breast carcinoma tissue." (PMID 26528430, 2015). "CLN3 overexpression in patients with no HER2 expression was significantly higher compared to those with positive HER2 breast cancer (p = 0.045)." (PMID 26528430, 2015). "CLN3 mRNA is overexpressed 3.5-fold in MCF7 cells compared to MCF10A cells, making MCF7 cells an excellent in vitro model to study the impact of CLN3 expression in breast cancer." (PMID 26528430, 2015). "Our findings confirm an association between high expression levels of the CLN3 gene and absence of HER2 expression in breast cancer patients, which increases the possibility of including it as a biomarker in breast cancer diagnostics." (PMID 26528430, 2015). "Down-regulation of CLN3, CTSD, and NAGLU in TET2 CD cells was further confirmed by RT-qPCR analysis, and expression of these three genes was shown to be anticorrelated with TET2 expression levels in the breast cancer TCGA cohort of patients (n = 1,218), validating our in vitro observations." (PMID 35351824, 2022). "In a study of human breast cancer samples, the absence of HER2 expression was found to be correlated with CLN3 overexpression." (PMID 35186475, 2022). "CLN3 mRNA is overexpressed in tumor vs. non-tumor breast tissue from FFPE and fresh samples, as well as in mouse MCF7 breast cancer compared to MCF10A normal cells." (PMID 26528430, 2015).
breast carcinoma (continued). "CLN3 overexpression did not correlate with lower or higher tumor grade, age, menopausal status, ER, PR, and HER2 expression, when comparing the level of CLN3 mRNA between breast cancer and the surrounding non-tumor tissue." (PMID 26528430, 2015).
neuroblastoma (5 papers, 2017 to 2020). Neuroblastoma (NB) is the most common solid, extracranial childhood tumor. "Either way, it is intriguing that we also see some mitochondrial localization of CLN3 in Drosophila given that an in vitro TAP-tag purification study identified CLN3 in complex with several mitochondrial transporters and inner membrane proteins in neuroblastoma cells." (PMID 28365214, 2017). "For example, proteomics-based analyses in SH-SY5Y human neuroblastoma cells revealed that PPT1/CLN1, CLN3, and CLN5 interact with 23, 58, and 31 proteins, respectively." (PMID 32430003, 2020). "Golabek and colleagues reported results obtained from expressing full‐length CLN3 fused with GFP in COS‐1, HeLa, and human neuroblastoma (SK‐N‐SH) cell lines." (PMID 31568712, 2019). "Finally DBH, SLC25A1, and SLC25A13 all interact with PPT1/CLN1, CLN3, and CLN5 in SH-SY5Y human neuroblastoma cells." (PMID 32430003, 2020).
neuronal ceroid lipofuscinosis 3 (5 papers, 2014 to 2024). A condition associated with mutation(s) in the CLN3 gene, encoding battenin. "Likewise, for CLN3, the 1.02 kb deletion, spanning exon 7 and 8, is present in 73% of all alleles causing ceroid neuronal lipofuscinosis type 3." (PMID 30548430, 2019).
retinal dystrophies (5 papers, 2017 to 2022). "Here, we described long‐term ophthalmological observation of a Japanese patient with isolated retinal dystrophy, identification of a novel homozygous CLN3 variant, and characteristic electron microscopic findings." (PMID 32441891, 2020). "Biallelic CLN3 gene variants have been found in either juvenile‐onset neuronal ceroid lipofuscinosis or isolated retinal dystrophy." (PMID 32441891, 2020). "In CLN3‐associated isolated retinal dystrophy, further TEM analysis is needed for elucidating frequency of fingerprint profiles." (PMID 32441891, 2020). "In conclusions, we described clinical and genetic characteristics of a Japanese patient with teenage‐onset isolated retinal dystrophy in whom a novel homozygous CLN3 missense variant was identified." (PMID 32441891, 2020). "In contrast, to date, 16 patients with biallelic CLN3 variants and isolated retinal dystrophy have been reported." (PMID 32441891, 2020). "Abundant lymphocyte vacuolization in a school‐aged child suffering from retinal dystrophy is pathognomonic for (classical) CLN3 disease." (PMID 32685355, 2020). "To date, CLN3‐associated JNCL or isolated retinal dystrophy has never been reported in the Japanese population." (PMID 32441891, 2020). "Lymphocyte vacuolization was rare with 1% to 3% of lymphocytes exhibiting some degree of vacuolization in both healthy controls and patients suffering from retinal dystrophy not caused by CLN3 disease, a relevant reference population." (PMID 32685355, 2020). "Although fingerprint profiles have never been reported in CLN3‐associated isolated retinal dystrophy, these profiles were observed, albeit infrequently, suggesting that frequency of the fingerprint profiles might depend on variant types." (PMID 32441891, 2020). "A critical role of inflammatory immune responses in the progression of retinal dystrophies in NCL has also been demonstrated in mouse models of CLN1, CLN3 and CLN6 disease." (PMID 33800998, 2021).
Lysosomal disease (4 papers, 2022 to 2025). "This implicates Cln3 in calcium regulation, likely due to its localisation at the contractile vacuole, a major calcium regulatory organelle, and suggests calcium dysregulation may be common to lysosomal disease cells." (PMID 35493081, 2022).
Alzheimer disease (3 papers, 2019 to 2025). A progressive, neurodegenerative disease characterized by loss of function and death of nerve cells in several areas of the brain leading to loss of cognitive function such as memory and language. "Activation of mTORC1 impairs autophagy in Alzheimer disease and JNCL also known as CLN3 disease." (PMID 33006978, 2020). "The use of serum ceramide levels as a biological marker has been established for other neurological and non-neurological diseases such as chronic kidney disease and Alzheimer's disease, but not in CLN3 disease." (PMID 30837943, 2019).
Brain atrophy (3 papers, 2014 to 2021). Partial or complete wasting (loss) of brain tissue that was once present. "In a previous study, we have shown that both fingolimod and teriflunomide treatment mitigates retinal thinning, axon degeneration, neuron loss and brain atrophy in CLN1 and CLN3 models." (PMID 33977263, 2021). "In mouse models of CLN3 Batten disease, disease progression results in whole brain atrophy, including region-specific atrophy in the cortex, hippocampus, thalamus, and cerebellum." (PMID 32601357, 2020). "This also seems to be valid for Cln3-/- mice, as retinal alterations (this study and unpublished observations) and regional brain atrophy occur only at advanced age." (PMID 24887158, 2014).
Cerebellar atrophy (3 papers, 2022 to 2023). Cerebellar atrophy is defined as a cerebellum with initially normal structures, in a posterior fossa with normal size, which displays enlarged fissures (interfolial spaces) in comparison to the foliae secondary to loss of tissue. "Disrupted metabolism and stored material in CLN3 cells lead to neurodegeneration manifested by cerebral and cerebellar atrophy and significant volume reduction in affected areas of the brain, visible on magnetic resonance (MR) images." (PMID 36576693, 2023). "Reduced levels of hydrolytic enzymes and mislocalized lysosomes have been observed in CLN3-mutant cells, and engorged lysosomes were described in SNX14 mutants, causing cerebellar atrophy in humans." (PMID 35351824, 2022). "Despite having relatively similar pathological endpoints of retinal, cerebral, and cerebellar atrophy, the documented clinical phenotypes, imaging and postmortem studies of CLN1 and CLN3 disease display some strikingly different features in how these diseases progress." (PMID 36438942, 2022).
GM1 gangliosidosis (3 papers, 2017 to 2020). A rare lysosomal storage disorder characterized biochemically by deficient beta-galactosidase activity and clinically by a wide range of variable neurovisceral, ophthalmological and dysmorphic features. "In addition, diseases such as CLN1, CLN3, CLN4, Farber disease, and GM1-gangliosidosis did not have orphan drug designations in 2013." (PMID 32267884, 2020).
autism (2 papers, 2014 to 2025). Persistent deficits in social interaction and communication and interaction as well as a markedly restricted repertoire of activity and interest as well as repetitive patterns of behavior. "CLN3 maps to chromosome 16p11.2 distal to regions previously associated with developmental delay, autism and obesity." (PMID 24705017, 2014). "Notably, CLN3 is frequently deleted or duplicated in individuals carrying atypical CNVs involving either the autism or the obesity-associated regions." (PMID 24705017, 2014). "Families recounted behavioural changes in both CLN2 and CLN3 disease mirroring attention deficit hyperactivity disorder (ADHD) or autism." (PMID 40355884, 2025).
Bull's eye maculopathy (2 papers, 2021 to 2023). Progressive maculopathy characterized by concentric regions of hyper- and hypopigmentation, with an initial foveal sparing and whose appearance is said to resemble the central target of a dart board. "The findings of an electronegative ERG with concurrent bull’s eye maculopathy in young age should prompt early neurological assessment for signs of neurodegeneration and referral for genomic investigation for CLN3 gene defects." (PMID 36964447, 2023). "It is important that CLN3 disease is considered in electronegative ERG-bull’s eye maculopathy patients even without neurological defect." (PMID 36964447, 2023).
Childhood onset (2 papers, 2014 to 2021). Onset of disease at the age of between 1 and 5 years. "In this study, we have shown that Dictyostelium contains an ortholog of CLN3, for which loss-of-function mutations in humans causes the childhood onset neurodegenerative disorder JNCL." (PMID 25330233, 2014).
CLN2 disease (2 papers, 2021 to 2022). "In contrast, the curvilinear storage materials observed in CLN3 neurons in this model are the dominant ultrastructure of storage bodies in CLN2 disease." (PMID 36453132, 2022).
Duchenne muscular dystrophy (2 papers, 2022 to 2024). Duchenne muscular dystrophy (DMD) is a neuromuscular disease characterized by rapidly progressive muscle weakness and wasting due to degeneration of skeletal, smooth and cardiac muscle. "ASO-mediated reading frame correction via induced skipping of symmetrical exons has shown promise in the FDA-approved ASOs targeting PTCs in Duchenne’s muscular dystrophy and also in preclinical studies in mice for the treatment of diseases such as CLN3 Batten." (PMID 35017302, 2022). "A previous study of DMD, which encodes dystrophin, has shown truncated proteins could rescue the Duchenne muscular dystrophy disease phenotypes if they escape NMD; this could be an interesting avenue to explore in CLN3 disease." (PMID 39367445, 2024).
Intellectual disability (2 papers, 2014 to 2015). "We compared the frequencies of rare CNVs (deletions and duplications combined) encompassing CISD2, PPT1, CLN3 and their gene network partners in unaffected controls and in individuals with intellectual disability phenotypes." (PMID 24705017, 2014).
mucolipidosis type IV (2 papers, 2020 to 2022). A lysosomal disease characterized by psychomotor delay, progressive visual impairment, and achlorhydria. "An altered localization of lysosomes, often clustered in the juxtanuclear area, seems to play a critical role also in the pathophysiology of Gaucher disease, neuronal ceroid lipofuscinosis type 3 (CLN3) and mucolipidosis type IV (MLIV)." (PMID 36285443, 2022). "Additionally, clustering of abnormal lysosomes in the perinuclear area was observed in ceroid lipofuscinosis type 3 (CLN3) and mucolipidosis type IV (ML-IV)." (PMID 32111095, 2020).
mucopolysaccharidoses (2 papers, 2017 to 2025). "However, it should be noted that a similar situation exists for other genes typically causing LSDs, namely subtypes of NCL and mucopolysaccharidosis: variants in CLN3, MFSD822, 23 and HGSNAT." (PMID 39199020, 2025).
multiple sclerosis (2 papers, 2019 to 2025). A progressive autoimmune disorder affecting the central nervous system resulting in demyelination. "Their study revealed significant differences in gut microbiota composition between Cln3−/− and wild-type mice, resembling alterations observed in other neuroinflammatory diseases such as multiple sclerosis." (PMID 40806324, 2025).
night blindness (2 papers, 2020). Inability to see clearly in dim light. "Non‐syndromic CLN3‐retinal phenotype includes both adult and early onset phenotype, mild nyctalopia, variable loss of visual acuity, and rod‐cone dystrophy with marked diminished rod function and significant but variable cone system dysfunction." (PMID 31736247, 2020). "In this study, we reported a patient with onset of night blindness in his teens and decreased visual acuity that progressively deteriorated over 13 years of follow‐up, who was found to carry a novel homozygous variant in the CLN3 gene." (PMID 32441891, 2020).